TNF (tumor necrosis factor)
Diseases named in the same sentence as TNF in open-access papers (continued):
Sharing a sentence is not in itself a finding about the gene and the disease.
tumor (continued). "Some studies found that TNF-α was increased by the Ganoderma lucidum extract complex in the tumor-bearing mice serum; polysaccharides from fresh fruiting bodies of Ganoderma lucidum were also able to greatly increase the TNF-α level in macrophage culture cells." (PMID 34305583, 2021). "TNF can either induce tumor cell death or survival depending on the conditions." (PMID 34809619, 2021). "Moreover, in cells treated only with butyrate, the expression of pro-apoptotic PTEN and anti-tumor TNFα increased (p ≤ 0.05), whereas anti-apoptotic BCL2 was reduced (p ≤ 0.001) compared to PA1B1 treatment." (PMID 34072741, 2021). "Many recent studies have described an emerged role of these death ligands (CD95L, TNF-α and TRAIL) in the enhanced production of various PICs; chemokines as well as TAPs that are linked with short survival and advanced tumor stages in various malignancies, including PDAC in an NFκB-dependent manner." (PMID 34771621, 2021). "Low levels of TNF-α could increase tumor growth by inducing recruitment of endothelial phenotypes of monocytes to the tumor site." (PMID 34630563, 2021). "Both the tumor and stromal cells of solid tumors secrete TNFα." (PMID 34885171, 2021). "TNF-α, IL-6, IL-10, and TGF-β are secreted by neoplastic cells and tumor-associated macrophages." (PMID 34574650, 2021). "However, a tumor-supporting role is believed to predominate as TNF-α has been shown to support tumor progression and metastasis, angiogenesis, and resistance to immunotherapies." (PMID 34064859, 2021). "CAFs are prolific producers of soluble factors implicated in tumor immunosuppression such as transforming growth factor beta (TGF-β), indoleamine-2,3-dioxygenase (IDO), prostaglandin E2 (PGE2), interleukin-6 (IL-6), tumor necrosis factor a (TNF-α), and VEGF." (PMID 35082797, 2021). "TNF-α is a proinflammatory cytokine that can lead to tumour cell necrosis." (PMID 34824593, 2021). "Hypothetically, the inhibition of IL-10 or the coactivation of CD40, IL-12, IL-8, and TNF-α, could repolarize these macrophages to the M1 phenotype, where reverse tumor development has been demonstrated." (PMID 34177892, 2021). "In summary, the inflammatory cytokine in the tumor microenvironment TNFα can synergistically augment the effect of T cells-derived cytokine, IFNγ, on the expression of immunosuppressive ligand, PD-L1 in HepG2 cells favoring tumor immune escape phenomenon." (PMID 34445462, 2021). "Considering that TNF can increase tumor vascular permeability and reduce drug penetration barriers, we tested the hypothesis that this nanodrug increased Doxo penetration in tumors." (PMID 33952242, 2021). "Furthermore, TNF-α expression was upregulated during the apoptosis of tumor cells by arsenic trioxide." (PMID 34880920, 2021). "Additionally, LLC tumor-induced increase of circulating TNF-α and IL-6 was abolished in TLR4 KO mice." (PMID 34093869, 2021). "Additionally, counterproductive vascular disruption mediated by TNF alpha for local tumor control is mostly limited at this dose selection." (PMID 33659041, 2021). "And NAA25 knockdown could increase apoptosis associated pathways, and reduce tumor associated pathways, like MYC, HIF1A, ERB2, MEK and TNF." (PMID 35096568, 2021). "Additionally, increased expression of miR-28 on murine T cells decreased their exhaustion state in B16-F10 tumor-bearing mice, as shown by the recovery of their capacity to secrete IL-2 and TNF-α." (PMID 34830805, 2021). "Moreover, it is known that the inflammation and associated with an upregulation of proinflammatory mediators such as IL-1β, IL-6, IL-8, and TNF-α, and prostaglandins by leukocytes play a major role in tumor development in TME." (PMID 34660256, 2021). "It was indicated that TNF-α up-regulated adhesion molecules and their ligands in the mixed culture system and facilitated the interaction of tumor cells with endothelial cells that might further promote brain metastasis." (PMID 34222020, 2021).
tumor (continued). "MiR-19a mimic was also administered in the AOM/DSS-induced CRC mice and induced pro-inflammatory cytokines (IL-6, TNF-α, IL-1β and IL-17a), tumor proliferation marker (Ki-67) and NF-κB signaling markers (p-P65 and COX-2) via targeting TNF-α-induced protein 3 (TNFAIP3)." (PMID 33921348, 2021). "This high specificity and stability can be used to deliver different tumor inhibiting factors such as tumor necrosis factor and truncated tissue factor, which lead to caspase mediated apoptosis and thrombosis in tumor vasculature, resulting in tumor cell death and tumor infarction." (PMID 34833427, 2021). "Notably, tumors with PD-L1 upregulation had a comparative increase in the expression of several genes involved in anti-tumor cytotoxicity such as IFNγ, TNFα, and IL-2." (PMID 34067257, 2021). "CD4 TILs also produced tumor necrosis factor (TNF)α that induced tumor cell senescence." (PMID 34201655, 2021). "Furthermore, the TNF-α/NF-κB signaling pathway is known to be involved in the tumor invasion and metastasis." (PMID 33435173, 2021). "TNFα activates the nuclear factor kappa-light-chain-enhancer of activated B cells (NFκB) transcription factor complex, which in turn induces several oncogenes and signaling pathways involved in tumor initiation and progression." (PMID 33859619, 2021). "However, some studies have found that increasing the serum levels of IL-2, IL-6, IL-12, and TNF-α in tumour-bearing mice regulates the growth and differentiation of lymphocytes and activate macrophages, playing a regulatory role in antitumour immunity." (PMID 34801005, 2021). "Likewise, PD‐L1 expression on PDAC cells was also positively related with macrophage infiltration in tumor stroma and infiltrating macrophages derived TNF‐α upregulated PD‐L1 expression on PDAC cells via NF‐κB pathway." (PMID 34423566, 2021). "On the contrary, it could reduce the TNF signaling pathways, which had been shown to promote tumor apoptosis when activated." (PMID 34799549, 2021). "The combination of CpG-oligonucleotide (ODN) and inhibitory interleukin-10 receptor antibody (anti-IL-10R) could induce tumor necrosis via a TNF-dependent pathway." (PMID 35096962, 2021). "Siglec-9 antibodies could increase cytotoxicity of healthy donor CD8+ T cells against anti-CD3-loaded P815 tumor cells and enhance IFNγ and TNFα production." (PMID 34966391, 2021). "These modes transmit death signals through signal molecules, such as cysteine-aspartic proteases (caspase) family and tumor necrosis factor-α (TNF-α) that have a wide and profound influence on tumor proliferation or death and even change the sensitivity of tumor cells to therapy." (PMID 34869390, 2021). "Besides, we found CD103+ CD3+ CD+ T cells secrete more IFN-γ, TNF-α and perforin than the other two subgroups in tumor." (PMID 33934206, 2021). "The evidence presented in our study convincingly demonstrates that TNF-α regulates the survival and proliferation of aggressive tumor cells by modulating the levels of critical assembly factors and subunits involved in mitochondrial respiratory chain supercomplexes organization and function." (PMID 33926547, 2021). "Interestingly, in TCs IL-6 and TNF production were suppressed compared to Covs and HDs potentially due an interaction between the immune system and the tumor." (PMID 34862879, 2021). "A recent study revealed that TNF-α may contribute to the migration of tumor cells by regulating prion protein levels." (PMID 33429846, 2021). "Thus, the ablation was associated with decrease in immune-suppressive CD206+ M2-like tumor-associated macrophages (TAM), an adjuvant to increase M1-like TAMs, which express MHC II, CD86, tumor necrosis factor alpha (TNF- α), IL-12, and IL-6." (PMID 33783613, 2021). "This study provides a novel mechanism by which ST6GAL1 may promote tumor cell survival within TNF-rich inflammatory tumor microenvironments." (PMID 33921986, 2021).
tumor (continued). "Moreover, the production of cytokines such as TNF-α enables the proliferation of neoplasms, tissue invasion, and angiogenesis through the upregulation of IL-8, VEGF, and βFGF." (PMID 34434197, 2021). "Previous studies showed that IL6 and Tumor necrosis factor α (TNFα) could promote Tregs proliferation in tumor sites." (PMID 34479503, 2021). "Osteoblastogenesis is not only inhibited by tumor-derived factors due to inactivation of pivotal signaling pathways or by induction of osteoblastic and osteocytic apoptosis as shown for Dickkopf-1, IL-6 and TNF-α." (PMID 34064859, 2021). "Tumor weight was significantly reduced by TNFα, Dox, or their combination (p < 0.001)." (PMID 34073371, 2021). "LPS from Salmonella can increase TNF-α and the tumor specific response of CD8+ T cells." (PMID 33717106, 2021). "TME cells may release growth factors and cytokines such as WNT, epidermal growth factor, TNF, IL-17, and IL-6 in response to therapy-induced tumour cell death, which promotes the survival of residual tumour cells and leads to treatment resistance." (PMID 35003085, 2021). "DAMPs and cytokines (such as tumor necrosis factor (TNF)-α, interleukin (IL)-6, and IL-1β) released from PDT treated cells cause acute inflammation and enhance infiltration of innate and adaptive immune cells to the irradiated tumor site." (PMID 37485044, 2021). "Indeed, TNFα is considered to be poorly cytotoxic/cytostatic against tumor cells, while it is particularly effective in inducing inflammation and vasculature destruction." (PMID 34712615, 2021). "There was evidence that all cytokines investigated, in relation to GC, have pro-tumour effects, although TNF, IFN-γ, and IL-10 may also participate in anti-tumour processes." (PMID 34944729, 2021). "At the beginning of its discovery, TNF was regarded as an induced factor of necrosis of malignant cells; however, accumulating studies suggest that TNF involves in tumorigenesis, inducing cancer cell survival and proliferation and facilitating tumor metastasis and escape from immunosurveillance." (PMID 32595734, 2020). "Dynamic changes in the values of tumor necrosis factor-alpha and IL-6 could reflect the cancer prognosis, depending on the tumor type, clinical progression, and cancer therapy." (PMID 32637353, 2020). "Tumor necrosis factor α (TNF-α) could regulate the tumor microenvironment balance by promoting chemokine secretion." (PMID 33158173, 2020). "The inflammatory cytokine TNF could be detected only in CD8αβ and TCRγδCD8− T cells, both in unaffected tissue and in tumor tissue." (PMID 32185408, 2020). "NO is more effective than TNF-α in mediating the killing of tumor cells by activated macrophages." (PMID 32149121, 2020). "In addition, the DCs supplied with the supernatant from M1-infected tumor cells produced much higher concentrations of IL-12, TNF-α, and IL-1β." (PMID 33311488, 2020). "In addition, pro-inflammatory cytokines, including TNF-α, IL-6, and IL-1β, play key roles in regulating inflammation and tumor progression." (PMID 32679895, 2020). "One is that NK cell can express apoptotic ligands such as TNF-related apoptosis-inducing ligand (TRAIL) and tumor necrosis factor (TNF) family members Fas-L and then interact with their related receptor on tumor cells which inducing the apoptosis of tumor cells." (PMID 33613544, 2020). "The maximum adhesion effect was observed in cell upon stimulating HUVECs with TNF‐a (5 ng/mL) and this binding was significantly reversed by the addition of anti‐E‐selectin antibodies, indicating that tumour adhesion mainly depends on ligand‐receptor interactions." (PMID 32985079, 2020).
tumor (continued). "Moreover, anti-TNF treatment enhanced the effect of double checkpoint blockade leading to increased numbers of tumor infiltrating T cells." (PMID 32486375, 2020). "Indeed, a CD13-specific single monomeric variable antibody domain tagged to tumor necrosis factor (TNF) or interferon (IFN)-γ has been used to kill tumors by targeting the tumor neovasculature." (PMID 32264921, 2020). "However, we confirmed the activation of STING, but the induction of type I IFN (IFNβ) in tumor cells was minor compared to the induction of TNFα, which expression can also be activated by STING." (PMID 33202881, 2020). "Moreover, CXCR4 expression in cancer cells increased upon treatment with tumor necrosis factor α (TNF-α), released both by TAMs and tumor cells." (PMID 32784743, 2020). "M1-type macrophages secreting immunogenic cytokines, such as IL-12 and TNF-a, improve the immune response that exerts inhibitory effects on tumor growth, and M2-type macrophages secreting immunosuppressive cytokines, such as IL-10 and TGF-β, impair antitumor immunity to enhance tumor growth." (PMID 34138195, 2020). "Finally, IHC found that preoperative FOBT-positivity in patients was significantly associated with higher TAMs infiltration and higher expression of IL-6 and TNF-α in tumor tissues than in the preoperative FOBT-negative group." (PMID 33643891, 2020). "Upon TLR activation, M1 cells produce pro-inflammatory cytokines such as TNF-α, IL-12, and IL-6, which may promote tumor cell killing through NOS2 production and activation of T cells." (PMID 33036138, 2020). "Furthermore, we observed a positive correlation between distal colon weight (as surrogate of tumor burden) and the mRNA levels of TNFα, NOS2, and COX-2." (PMID 33489875, 2020). "Many studies have reported that a series of proangiogenic cytokines are enriched in tumor-derived EVs, such as VEGF, fibroblast growth factor (FGF), interleukin (IL)-6, IL-1α, and tumor necrosis factor alpha (TNF-α), which directly contribute to tumor angiogenesis." (PMID 33628730, 2020). "Clinical studies have shown that KLTi exerts inhibitory effects on the generation of neovascularization in tumor cells, increasing macrophages, further inducing lymphocytic cytokines and tumor necrosis factor, thereby enhancing the immunity capacity of patients." (PMID 32047528, 2020). "TNF-α/ TNFR1 signaling participates in the proliferation of oval cells during the preneoplastic stage of liver carcinogenesis and loss of TNFR1 reduces the incidence of tumor formation." (PMID 32929358, 2020). "It has been also shown that suppressing the increased expression of inflammation-related factors such as TNF is considered to potentially suppress the migration of macrophages into tumor tissues and regulate inflammatory changes in the tumor environments, respectively." (PMID 32870935, 2020). "Pro-inflammatory molecules, such as interleukin-6 (IL-6), tumor necrosis factor alpha (TNFα), IL-1, and interferon-γ, derived from the immune system or from the tumor itself and glucocorticoids, are increased in plasma of rodents and patients with different cancers." (PMID 33255345, 2020). "Mast cells secrete TNF-α, an inducer for tumor angiogenesis." (PMID 33177244, 2020). "TNF-α can regulate the tumor microenvironment balance by promoting chemokine secretion." (PMID 33158173, 2020). "Interestingly, there was an increase in tumor TNF-α and decrease in IL-10 levels in animals treated with fruti, showing a pro-inflammatory effect of fruti." (PMID 33020521, 2020). "Tumor-associated macrophage (TAM) phenotype analysis showed that microbial ablation resulted in a decrease in immune-suppressive CD206+ M2-like TAMs and an increase in M1-like TAMs, which expressed higher MHC II, CD86, TNF-α, IL-12, and IL-6." (PMID 33520714, 2020).
tumor (continued). "Complex stromal and tumour cell interactions have previously been shown to be potent drivers of resistance during MAPK inhibitor therapies through the secretion of different growth factors such as TNFα, HGF and others." (PMID 31323160, 2020). "TNF-α may be a tumor-promoting factor in NPC, as TNF-α expression has been observed in both primary NPC specimens and serum derived from NPC patients, and can significantly predict the risk of distant metastasis in NPC patients." (PMID 32863767, 2020). "TNF-α may be massively expressed by cancer cells in the tumor microenvironment and to a lesser extent by Th1 cells: a higher proportion of tumor cells in the PBS control group showed increased mRNA levels of TNF-α in the tumor microenvironment." (PMID 32903495, 2020). "Our results also showed that TNFα from TAMs is one of the suppressors of tumor immunity." (PMID 32518979, 2020). "The final outcome may be dependent not only on the type of tumor but also on time frame of this modulatory effect and the availability and presentation of its canonical ligand TNF-α." (PMID 33202705, 2020). "This indicated that LIPUS could reduce the metastasis of tumor by decreasing the expression levels of TNF-α and IL-6." (PMID 32936241, 2020). "Moreover, Hyp-PDT can reduce the cancer cell-secreted tumor-promoting cytokines such as Granulocyte-macrophage colony-stimulating factor (GM-CSF), IL-6, and TNF." (PMID 32340275, 2020). "In addition, IFN-DCs exhibit cytotoxic activity against various tumor cell lines, express a wide range of cytotoxic ligands (TNFα, TRAIL, FasL, perforin), and also secrete granzyme B, which is barely produced by IL-4-DCs." (PMID 32326230, 2020). "Inhibition of TNFα signaling with IκB kinase inhibitors significantly improved the effectiveness of MAPK pathway inhibitors by targeting not only the melanoma cells but also the tumor microenvironment." (PMID 32656079, 2020). "Moreover, metformin increases the number of CD8+ tumor-infiltrating lymphocytes and also protects them from apoptosis and exhaustion which is characterized by decreased production of IL-2, TNFα, and IFNγ." (PMID 32296640, 2020). "In addition, the cytokines IL-1α, IL-1β, IL-6, IL-17A, and TNF-α promote tumor initiation, progression, angiogenesis, and metastasis in many human malignancies, including CRC, and our findings are consistent with previous studies." (PMID 33488574, 2020). "Whether MAGI1 is part of this mechanism, and whether this protein is possibly regulated by other tumor-promoting mediators of inflammation (e.g., TNF, IL6) is an attractive hypothesis that deserves further investigations." (PMID 31963297, 2020). "Additionally, the box-and-whiskers plots indicated that WNT10A, PDGFA, and TNF were out of normal distribution due to extremely high expression in many tumor patients which were individually labeled with dots." (PMID 32434423, 2020). "Indeed, tumor-derived sEVs can stimulate a significant release of various cytokines, including IL-6, TNF, and TGF-β by CD14+ monocytes from healthy donors and can promote suppression of their functions as well as the proliferation of T cells." (PMID 32015297, 2020). "Tumor necrosis requires a high concentration of TNFα, which is often accompanied by high toxicity." (PMID 33214550, 2020). "Activated basophils release mediators, such as granzyme B, TNFα and histamine, which may act directly to regulate tumor growth." (PMID 32645919, 2020). "Inflammation in the tumor microenvironment and production of inflammatory cytokines such as TNF-α, IL-1β, and IFNγ (that could also be induced by HCMV) may lead to further induction of PRLR." (PMID 32121009, 2020). "To reveal whether the senescence induction in tumor cells is dependent on IFN-γ/TNF-α produced by IL-2/IL-12/IL-18-stimulated γδ T cells, we neutralized IFN-γ/TNF-α by anti-IFN-γ antibody or anti-TNF-α antibody or both antibodies." (PMID 31947966, 2020).